CSMD3 (CUB and Sushi multiple domains 3)
Description:
Involved in dendrite development.
Tractability: Antibody: UniProt places it where antibodies can reach, with medium confidence; UniProt predicts a signal peptide or a membrane-spanning region; its Gene Ontology location is reachable by antibodies, with medium confidence; the Human Protein Atlas places it where antibodies can reach. PROTAC: its protein half-life has been measured.
Gene: Protein-coding gene on chromosome 8 (112,222,928 to 113,436,939, reverse strand). Ensembl gene ENSG00000164796.
Subcellular location: Cell membrane
Subcellular location (Human Protein Atlas): Plasma membrane
Gene Ontology:
Biological process: regulation of dendrite development
Cellular component: plasma membrane
Genetic constraint (gnomAD): Loss-of-function variants: 102 observed, 259.32 expected, observed/expected ratio (o/e) 0.39, 90% interval 0.33 to 0.46. The upper end of that interval is the gene's LOEUF score, 0.46, which puts it in group 2 of 6, group 1 being the genes least tolerant of losing a copy. Missense variants: 2,886 observed, 3,234.8 expected, observed/expected ratio (o/e) 0.89, 90% interval 0.86 to 0.92. Synonymous variants: 1,186 observed, 1,131.7 expected, observed/expected ratio (o/e) 1.05, 90% interval 1 to 1.1.
Homologues: Orthologues: chimpanzee CSMD3 (99% identical), macaque CSMD3 (99% identical), mouse Csmd3 (98% identical), pig CSMD3 (98% identical), rat Csmd3 (97% identical), rabbit CSMD3 (97% identical), tropical clawed frog CSMD3 (85% identical), guinea pig CSMD3 (78% identical), zebrafish csmd3b (76% identical), zebrafish csmd3a (73% identical). Paralogues in human: CSMD1 (61% identical), CSMD2 (58% identical), SVEP1 (21% identical), CR1 (11% identical), CR2 (8% identical), SEZ6L (6% identical), SEZ6 (6% identical), CFH (6% identical), SELP (5% identical), PAPPA2 (5% identical), SEZ6L2 (5% identical), PAPPA (5% identical), and 27 more.
Diseases named in the same sentence as CSMD3 in open-access papers:
CSMD3 is named in the same sentence as 62 diseases in open-access papers, as found by Europe PMC text mining. Sharing a sentence is not in itself a finding about the gene and the disease. The quoted sentences say what the papers report.
ovarian carcinoma (13 papers, 2016 to 2024). A malignant neoplasm originating from the surface ovarian epithelium. "A recent study in human ovarian cancers showed a significant correlation between CSMD3 mutation, elevated tumor mutation burden and shorter overall survival." (PMID 37079639, 2023). "CSMD3 mutation is highly correlated with increased tumor mutational burden and poor clinical prognosis in ovarian cancer." (PMID 38067373, 2023). "Ovarian carcinoma patients with CSMD3 mutation had sustained responses to anti-PD1 without prior chemotherapy." (PMID 34970479, 2021). "Previous studies have revealed the function of CSMD3 in dendritic cells and regulation of HMCN1 in fibroblasts, suggesting these genes may regulate various components of the ovarian cancer microenvironment." (PMID 35735060, 2022). "For example, CSMD3 and ZFHX3 are involved in ovarian cancer and endometrial carcinoma, respectively, which indicated that integration of HPV may lead to malfunctions of host oncogenes and tumor suppressors." (PMID 35058971, 2021).
lung carcinoma (12 papers, 2014 to 2024). "LRP1B, KMT2D, RNF213 and CSMD3 gene mutations were significantly more common in lung cancer than in benign disease (P < 0.05)." (PMID 33200540, 2021). "Recent studies showed that loss of CSMD3 increases proliferation of airway epithelial cells and may be involved in tumorigenesis in lung cancer." (PMID 24576404, 2014). "Mutation of CSMD3 in non‐small‐cell lung cancer leads to increased proliferation of airway epithelial cells, and abnormal methylation of FBN2 is a biomarker for lung cancer." (PMID 34951053, 2022). "KMT2D, CSMD3 and LRP1B were mutated in 15%, 10% and 10% of lung cancer patients, but KMT2D and CSMD3 were mutated in 25% and 12.5% of benign diseases." (PMID 33200540, 2021). "In the training set, the RNF213, LRP1B, KMT2D and CSMD3 genes had statistically significant differences in the sequenced data in lung cancer compared to benign disease." (PMID 33200540, 2021). "In the training set, RNF213, KMT2D, CSMD3 and LRP1B were mutated more frequently in early‐stage lung cancer than in benign disease." (PMID 33200540, 2021). "High expression of RNF213, KMT2D and CSMD3 was observed in lung cancer tissues, and low expression of these genes was observed in benign disease tissues." (PMID 33200540, 2021). "In the training set, the RNF213, KMT2D, CSMD3 and LRP1B genes were mutated more frequently in early‐stage lung cancer (27 cases) than in benign nodules (15 cases) (P < 0.05)." (PMID 33200540, 2021). "The number of missense mutations in the LRP1B, KMT2D, RNF213 and CSMD3 genes was eight (8/27, 29.6%), seven (7/27, 25.9%), seven (7/27, 25.9%) and six (6/27, 22.2%) in the lung cancer group, respectively, and none of the genes were mutated in the benign disease control group." (PMID 33200540, 2021). "The number of the test genes RNF213, KMT2D, CSMD3 and LRP1B detected in lung cancer samples was five, five, three and two, respectively." (PMID 33200540, 2021). "The RNF213 gene was mutated in 25% of lung cancer patients and was not mutated in benign diseases, but KMT2D, CSMD3 and LRP1B were mutated less in both groups." (PMID 33200540, 2021).
lung adenocarcinoma (8 papers, 2014 to 2025). A carcinoma that arises from the lung and is characterized by the presence of malignant glandular epithelial cells. "CSMD3 mutations were recently found in lung adenocarcinomas, with more frequent mutations in invasive compared to in situ tumors (8% vs. 3%)." (PMID 39235515, 2025). "While mutations in Dcc, Csmd3, and Fhit are rather uncommon in human lung adenocarcinomas, deletions or allelic imbalances occur frequently and are considered early events in human lung tumorigenesis." (PMID 35295134, 2021). "Our result suggested that mutations of TTN, MUC16 and CSMD3 may be associated with low expression of LINC02126 in lung adenocarcinoma." (PMID 36357869, 2022). "We identified alterations in genes involved in chromatin remodeling (PBRM1, SETD2), oxidative stress (CUL3, SOD2), immune response (CSMD3, SYK), and gamma-aminobutyric acid receptor signaling (GABRD, GABRG1) in lung adenocarcinoma." (PMID 24576404, 2014).
autism spectrum disorder (5 papers, 2010 to 2024). A spectrum of developmental disorders that includes autism, and Asperger syndrome. "CSMD3 encodes a transmembrane protein selectively expressed in adult and fetal brains and is a strong candidate for autism spectrum disorders and benign adult familial myoclonic epilepsy." (PMID 24523945, 2014). "CSMD3 was reported to have an impact on autistic spectrum disorders and immunity via QTL information." (PMID 37959106, 2023). "In addition to CSMD1, heterozygous de novo and inherited missense CSMD3 variants were recently described as the genetic basis for a NDD characterized by ID and autism spectrum disorder." (PMID 38816421, 2024).
colorectal cancer (5 papers, 2014 to 2022). A primary or metastatic malignant neoplasm that affects the colon or rectum. "CSMD3 is involved in dendrite development and germline variants in this gene have been linked to colorectal cancer." (PMID 33810183, 2021). "The non‐synonymous mutation of CSMD3 has been identified in familial colorectal cancer but not in healthy controls." (PMID 35735060, 2022). "SEISMIC also reported several large cancer genes not detected in the other studies, including CSMD3 (3,707 amino acids) in UCEC and STAD, and LRP1B (4599 amino acids) in STAD and colorectal cancer (CRC)." (PMID 36396655, 2022).
hepatocellular carcinoma (5 papers, 2016 to 2025). A malignant tumor that arises from hepatocytes. "In hepatocellular carcinoma, mutations of CSMD3 identified in plasma cell-free tumor DNA were found to be associated with a shorter overall survival." (PMID 39196408, 2024). "Inhibition of miR-873 expression resulted in upregulation of CSMD3 in several hepatoma cell lines, indicating that CSMD3 is indeed a target of miR-873." (PMID 27918551, 2016).
serous ovarian cancer (5 papers, 2014 to 2022). "CSMD3 mutations have been characterized as tumors with high concentrations of T cells in patients with high-grade serous ovarian carcinoma." (PMID 34277450, 2021). "In addition, this panel is targeting “hotspot” region of genes that are frequently mutated in human cancer thus other infrequently altered genes but of significance to serous ovarian cancers might have been excluded such as ARID1A, BRCA1, BRCA2, CSMD3, NF1, CDK12, FAT3 and GABRA6." (PMID 25404506, 2014).
breast carcinoma (4 papers, 2018 to 2024). "TAF2 has been reported to be amplified in breast cancer and CSMD3 as mutated in Esophageal Squamous Cell Carcinoma." (PMID 39457378, 2024). "There are a few SV regions that harbouring breast cancer associated tumour suppressor genes, such as PTPRD in HCI008 model and CSMD3 in HCI012 model." (PMID 36153537, 2022).
colon carcinoma (4 papers, 2014 to 2023). "While rarely altered in human cancers in general (<0.5% of all cases), the incidence of CSMD3 disruption in UC (~14% of cases) is among the highest across cancer subtypes, along with ovarian, breast, gastric and colon carcinomas." (PMID 37079639, 2023).
lung squamous cell carcinoma (4 papers, 2021 to 2025). "A poor survival outcome was associated with CSMD3 wildtype, and the same result was discovered in lung squamous cell carcinoma." (PMID 36532024, 2022). "Meanwhile, the consumption of CSMD3 is known to augment the survival of squamous cell lung cancer tumor cells." (PMID 36267961, 2022).
prostate carcinoma (4 papers, 2023 to 2024). A carcinoma that arises from epithelial cells of the prostate gland. "CUB and Sushi multiple domains 3 (CSDM3) have been shown to be one of the 10 most recurrently mutated genes in prostate cancer and SNPs in CSMD3 are associated with the risk of prostate cancer in Hispanic men." (PMID 38067373, 2023). "We observed enrichment of mutations in several genes including understudied genes such as EYA1, CSMD3, FLT4, NCOR2, and PCDH15 and found that mutations in EYA1 and CSMD3 are associated with a poor outcome in prostate cancer." (PMID 38067373, 2023). "Future directions for this work include further characterization of EYA1, CSMD3, FGFR3, and PCDH15 in prostate cancer metastases and the roles of oxidative phosphorylation and FGFR3 in prostate cancer health disparities." (PMID 38067373, 2023).
endometrial carcinoma (2 papers, 2019 to 2021). A malignant tumor arising from the epithelium that lines the cavity of the uterine body.
esophageal cancer (2 papers, 2022). A primary or metastatic malignant neoplasm involving the esophagus. "CSMD3 mutations are related to favorable clinical outcomes in esophageal cancer." (PMID 34951053, 2022).
esophageal squamous cell carcinoma (2 papers, 2023 to 2024). Esophageal squamous cell carcinoma (ESCC) is a type of esophageal carcinoma (EC) that can affect any part of the esophagus, but is usually located in the upper or middle third. "CYP2E1 genetic polymorphism affects the susceptibility of multiple tumors, while CSMD3 mutation is significantly linked to prognosis in some cancers such as non-small cell lung cancer, esophageal squamous cell carcinoma, but their specific mechanism still needed further exploring." (PMID 37264314, 2023).
liposarcoma (2 papers, 2018 to 2023). A usually painless malignant tumor that arises from adipose tissue. "Mutations in CSMD3 have been reported in dedifferentiated liposarcomas and synovial sarcomas." (PMID 37106027, 2023). "In our study we also noted deleterious mutations in 7 other genes (CTNNB1 (R151H), MECOM (R208C), ZNF536 (T688M), EML4 (W729L), CSMD3 (P627S), PBRM1 (N639K), PPP1R3A (C788Y)) that have also not been described previously in WD/DD liposarcoma." (PMID 29731991, 2018).
neuroblastoma (2 papers, 2015 to 2024). Neuroblastoma (NB) is the most common solid, extracranial childhood tumor. "Kaplan-Meier plots showed a significant association between increased expression of CFHR3, MDFIC, CSMD3, FOXP2, or RALYL (genes with gains in coding regions) and poor OS in patients with neuroblastoma." (PMID 26159519, 2015).
non-small cell lung carcinoma (2 papers, 2023). A group of at least three distinct histological types of lung cancer, including non-small cell squamous cell carcinoma, adenocarcinoma, and large cell carcinoma.
oral cancer (2 papers, 2022 to 2025).
autism (1 paper, 2011). Persistent deficits in social interaction and communication and interaction as well as a markedly restricted repertoire of activity and interest as well as repetitive patterns of behavior. "Other previously reported autism candidate genes with suggestive roles in neurite regulation include PCDH9 (1.76E-03), CDH9 (6.00E-03) and CSMD3 (2.10E-02)." (PMID 21247446, 2011).
bladder cancers (1 paper, 2023). "CSMD3 was mutated in five samples from the present study (14% of cases, comprising 2/8 POSV595E and 3/28 UDV595E samples), and was also highlighted as a recurrently mutated gene in bladder cancers of both dogs and people." (PMID 37079639, 2023).
chronic hepatitis B (1 paper, 2024). "Five patients had liver diseases (polycystic liver disease, liver fibrosis, liver cirrhosis, or chronic hepatitis B) with an average of 97 small somatic variants, including nonsilent variants in ARID1A, CSMD3, and KEAP1 and one copy gain of PBX1." (PMID 38877653, 2024).
head and neck cancer (1 paper, 2020). A primary or metastatic malignant neoplasm affecting the head and neck.
melanoma (1 paper, 2022). A malignant, usually aggressive tumor composed of atypical, neoplastic melanocytes. "Interestingly, 777T/I, 519L/F, and 1312G/R mutations on PAPPA2, and 231P/L and 171E/K mutations on CSMD3 were only observed in responders with melanoma or NSCLC." (PMID 36139377, 2022).
metastatic tumor (1 paper, 2016). "Unique mutations in PCLO and CSMD3 in P3A and P3B, respectively and FLG, MLL3 and SPEN in metastatic tumor M3A are listed in the branches." (PMID 27034009, 2016).
morbid obesity (1 paper, 2021). An excess of body weight, normally defined as an individual with a body mass index greater than 35 or a body weight greater than one hundred percent of ideal body weight. "Although the biological function of CSMD3 has not been fully understood, this gene is associated with alcohol exposure and its genetic alteration is associated with morbid obesity." (PMID 34635168, 2021).
Obesity (1 paper, 2024). Accumulation of substantial excess body fat. "Significant associations were observed between morbid obese Han Chinese and CSMD3 (obesity related, IMPC) and ERBB4." (PMID 38483771, 2024).
penile tumors (1 paper, 2022). "We also described, for the first time, UTRs variants (KDR, CARD11, CSMD3, and TLX3), impacting the miRNAs’ binding sites in penile tumors." (PMID 35884575, 2022).
prostate tumors (1 paper, 2023). "Integrative genomic analysis of primary prostate tumors and associated LNM demonstrated the enrichment of mutations in several genes including both well-established oncogenes and tumor suppressors and understudied genes such as EYA1, CSMD3, FLT4, NCOR2, and PCDH15." (PMID 38067373, 2023).
rectal tumors (1 paper, 2025).
sarcoma (1 paper, 2023). A usually aggressive malignant neoplasm of the soft tissue or bone. "Recently, sarcomas harboring an immune-hot phenotype were demonstrated to carry the highest frequencies of CSMD3 mutations." (PMID 37106027, 2023).
Williams-Beuren syndrome (1 paper, 2013). "Five patients who had deletions in NRXN1 had a second CNV implicated in neurodevelopmental disorder: a CNTNAP2 and CSMD3 deletion in patients with exonic NRXN1 deletions, and a Williams-Beuren syndrome deletion and two 22q11.2 duplications in patients with intronic NRXN1 deletions." (PMID 25408897, 2013).